CASP1 (caspase 1)
Diseases named in the same sentence as CASP1 in open-access papers (continued):
Sharing a sentence is not in itself a finding about the gene and the disease.
keloid (4 papers, 2020 to 2024). An irregularly shaped, elevated mark on the skin caused by deposits of excessive amounts of collagen during wound healing. "Here, we confirmed keloid NLRP3 activation (cleaved caspase-1 [P < 0.05], IL-1β [P < 0.05], IL-18 [P < 0.01]) and upregulation in Glut1 (P < 0.001) and glycolytic enzymes." (PMID 32750036, 2020). "Knockdown of Notch1 with siRNA significantly down-regulated increased levels of NF-κB, NLRP3, ASC, and an intermediate form of caspase-1 in keloid fibroblasts." (PMID 33126764, 2020). "We determined if NLRP3-mediated inflammation is still activated beyond this time point in keloids by measuring protein levels of cleaved caspase-1 and IL-1β in keloids compared with burn skin (7–10 days after burn, average age 53 years and total body surface area [TBSA] 39%) and normal skin." (PMID 32750036, 2020). "However, the expression of cleaved caspase-1, IL-1β and IL-18 was upregulated in human keloids 7–10 days after burn compared with burn and normal skin, suggesting NLRP3-mediated inflammation in keloids and possibly contributing to a persistent inflammatory state." (PMID 38957662, 2024). "Although protein levels of ASC and an intermediate form of caspase-1 were not significantly different between keloid and normal fibroblasts, protein levels of nuclear factor kappa B (NF-κB), a known primer of the NLRP3 inflammasome, increased in keloid fibroblasts." (PMID 33126764, 2020).
leishmaniasis (4 papers, 2012 to 2024). Infectious disease that is transmitted through the bite of hematophagous female phlebotomine sand flies. "Still, our data demonstrated an overall increased expression of inflammasome-related genes such as Gsdmd, Nlrp3, Casp1, Casp4, Il1b, Ifng, Tnfa, Il10, and Il17a when we compared Leishmaniasis patients with controls." (PMID 36828815, 2023). "The analysis of IL-1β and other proteins that participate in inflammation like caspase-1 and -5 or NALP3, in a larger group of patients, could possibly help define to what extent polymorphisms and enhanced production of IL-1β contribute to various clinical forms of leishmaniasis." (PMID 22629474, 2012).
male infertility (4 papers, 2016 to 2025). The inability of the male to effect fertilization of an ovum after a specified period of unprotected intercourse. "The results emphasized the regulatory role of JAK2/STAT3, NLRP3/Caspase-1 signaling in testicular tissue maintenance to resist PbAc-induced dysfunctions and male infertility." (PMID 40356721, 2025). "When combined with caspase-1 induced cell death, the NLR\NALP3 axis could serve as pathological pathway for male infertility." (PMID 26744177, 2016).
neuropathic pain (4 papers, 2016 to 2023). Chronic pain caused by damage to nerve fibers. "There is increasing evidence that CASP1, CASP6, and CASP11 activation is involved in microglia activation and the maturation of proinflammatory cytokines in inflammatory and neuropathic pain conditions." (PMID 28270702, 2017). "Our study revealed that SNI induced an obvious and significant aggregation of NALP1, caspase-1, and the adaptor protein ASC, which suggests that the NALP1 inflammasome is activated during neuropathic pain." (PMID 27381056, 2016).
oral cancer (4 papers, 2021 to 2025). "In an in vitro model employing OSCC cells and an in vivo xenograft model of oral cancer, an NLRP3 inflammasome inhibitor BAY-117082 significantly reduced NLRP3, ASC, caspase-1, IL-1β, and IL-18 expression and a reduction in tumor growth." (PMID 38904007, 2024).
osteomyelitis (4 papers, 2021 to 2025). An acute or chronic inflammation of the bone and its structures due to infection with pyogenic bacteria. "Preclinical models have associated PANoptosis with sterile inflammatory conditions, exemplified by the prevention of chronic recurrent multifocal osteomyelitis in mice through the concurrent deficiency of Caspase-1, Caspase-8, and RIPK3—key PANoptosis components." (PMID 40664640, 2025). "The expressions of pyroptosis-related proteins, NLRP3, caspase-1, and GSDMD were significantly increased in mouse osteomyelitis model induced by Staphylococcus aureus and infectious bone fragments of patients with osteomyelitis." (PMID 33215255, 2021). "In a mouse osteomyelitis model, pyroptosis-related proteins were upregulated, whereas Ac-YVAD-CMK, a specific Caspase-1 inhibitor, not only inhibited the increases of Caspase-1 and GSDMD in mice induced by bacteria, but also helped to restore the osteogenic characteristics." (PMID 34646239, 2021).
pulpitis (4 papers, 2015 to 2025). Inflammation of the dental pulp. "HIF-1α served as a positive regulator of NLRP3/ASC/CASP1 inflammasome pathway activation via NF-κB signaling in HDPFs in the sterile pulpal inflammation and caries-related pulpitis microenvironment." (PMID 39343901, 2024). "Previous studies have reported that activation of the NLRP3/CASP1 inflammasome pathway in HDPFs promotes the progression of pulpitis." (PMID 39343901, 2024). "A significant difference in the mRNA level of caspase-1 and IL-1β was observed only between normal pulp and pulp with irreversible pulpitis." (PMID 25684031, 2015). "The expression of the caspase-1 gene is also increased in pulp showing irreversible pulpitis compared with normal pulp and pulp with reversible pulpitis." (PMID 25684031, 2015). "In conclusion, this report demonstrates that tissue with irreversible pulpitis contains more functional NLRP3/caspase-1 than healthy pulp and pulp with reversible pulpitis tissue." (PMID 25684031, 2015). "The expression of NLRP3, caspase-1 and IL-1β was analysed by the detection of the relevant protein and mRNA in normal pulp and in pulp with reversible pulpitis or irreversible pulpitis." (PMID 25684031, 2015). "We analysed the presence, localization and quantity of NLRP3 and caspase-1 in healthy dental pulp and pulp showing reversible pulpitis or irreversible pulpitis." (PMID 25684031, 2015). "Here, we found that the NLRP3/caspase-1 inflammasome pathway can be activated in pulp tissues with irreversible pulpitis." (PMID 25684031, 2015). "Furthermore, NLRP3 inflammasome is a critical regulator for immune reactions during pulpitis progression, which activates caspase-1 into cleaved-caspase-1." (PMID 40414936, 2025). "Caspase-1 is present in its active (cleaved) form only in pulp tissue with irreversible pulpitis." (PMID 25684031, 2015). "The expression of pro-caspase-1 protein was detected in all human dental pulp tissue specimens, whereas the expression of active caspase-1 (p20) was detected only in pulp with irreversible pulpitis." (PMID 25684031, 2015). "Meanwhile, in pulpitis tissue, the protein level of NLRP3, cleaved caspase-1 and cleaved IL-1β, which also play a key role in inflammation and pyroptosis, was significantly increased." (PMID 34887391, 2021). "Furthermore, we simulated the caries-related pulpitis microenvironment and revealed that LPS and hypoxic conditions had synergistic effects in promoting the NLRP3/ASC/CASP1 inflammasome pathway activation via NF-κB signaling in HDPFs." (PMID 39343901, 2024). "However, in tissue showing irreversible pulpitis, the odontoblast layers were disrupted and dental pulp cells displayed extensive staining for NLRP3 and caspase-1." (PMID 25684031, 2015).
thrombosis (4 papers, 2016 to 2025). "Colocalized NETs and Caspase-1 and platelet recruitment were observed at the site of thrombosis." (PMID 34926629, 2021). "For instance, down-regulation of miR-513c-5p in the peripheral blood mononuclear cells accelerates pyroptosis by up-regulating Caspase-1 and contribute to the pathogenesis of deep vein thrombosis (DVT)." (PMID 40372489, 2025).
type 1 diabetes (4 papers, 2019 to 2023). "Inhibition of caspase-1 or deletion of IL-1 receptor prevented IL-1β-dependent formation of acellular capillaries in retinas of type 1 diabetic mouse models." (PMID 32492941, 2020). "Patients with type 1 diabetes exhibited increased circulating mDNA as well as caspase-1 and IL-1β activation." (PMID 32009974, 2019). "Further, some authors reported that intrarenal NLRP3/Caspase 1 inflammasome activation was present in both the db/db mouse and the murine STZ-induced type 1 diabetes model." (PMID 31540220, 2019).
vasculitis (4 papers, 2017 to 2023). "In LCWE-injected mice, this was associated with decreased severity of LCWE-induced KD vasculitis and significant reductions of both tissue Caspase-1 activity and systemic IL-1β levels." (PMID 34403365, 2021). "Previous studies indicate that in LCWE-induced KD vasculitis, monocytes and macrophages are the main sources of IL-1B, while neutrophils and eosinophils also express transcripts (Il1b, Nlrp3, Casp1, and Pycard) and have the capacity to produce IL-1B." (PMID 37279077, 2023).
Alcohol (3 papers, 2022 to 2025). "The Szabo laboratory found that mice deficient in ASC or in caspase-1 have decreased hepatic and systemic IL-1β levels and showed protection from alcohol-induced liver damage, demonstrating the dependence on the adaptor protein ASC and caspase-1 on the increase of IL-1β in ALD." (PMID 35264978, 2022).
amyotrophic lateral sclerosis (3 papers, 2012 to 2019). Amyotrophic lateral sclerosis (ALS) is a neurodegenerative disease characterized by progressive muscular paralysis reflecting degeneration of motor neurons in the primary motor cortex, corticospinal tracts, brainstem and spinal cord. "Similarly, other research teams have reported increases in the expression and activity of NLRP3, IL-1β, IL-18 and caspase-1 in plaques of MS patients and the tissues of amyotrophic lateral sclerosis (ALS) (or motor neurone disease) patients." (PMID 29052145, 2018).
anemia (3 papers, 2022 to 2024). A reduction in the number of red blood cells, the amount of hemoglobin, and/or the volume of packed red blood cells. "In chronic inflammation, inflammasomes activate caspase-1 and skew the differentiation of HSPCs toward myeloid cells, resulting in neutrophilia and anemia." (PMID 39474425, 2024). "This activation also results in degradation of the erythroid transcription factor GATA1, through caspase-1 activation, changing the ratio between GATA1 and the myeloid transcription factor PU.1 favoring myeloid commitment, maturation arrest, and anemia." (PMID 36835307, 2023). "Mechanistically, caspase-1 degraded the master erythroid transcription factor, GATA binding protein 1, provoking anemia and myeloid lineage bias that was reversed by cGAS inhibition in vitro and in Tet2–/– hematopoietic stem and progenitor cell–transplanted mice." (PMID 35788117, 2022).
aortic aneurysm (3 papers, 2020 to 2024). A ruptured aneurysm located in the wall of the proximal portion of the descending aorta proceeding from the arch of the aorta. "Although the direct contribution of the NLRP3-Caspase-1 inflammasome to MMP-9 activation remains to be demonstrated in human aortic aneurysms, targeting this pathway with MCC950 is a promising approach for preventing aortic destruction." (PMID 34572082, 2021).
autoimmune hepatitis (3 papers, 2018 to 2024). Hepatitis caused by autoantibodies. "Exosomes and exosomesmiR-223(+) significantly reversed autoimmune hepatitis by downregulating cytokines such as NLRP3 and caspase-1, while exosomesmiR-223(−) did not exert protective effects in the experimental model of autoimmune hepatitis." (PMID 32883343, 2020).
B-cell lymphoma (3 papers, 2020 to 2021). "Consistent with our results, primary effusion B-cell lymphoma cells showed that IFI16 mediated caspase-1 inflammasome activation." (PMID 32577124, 2020). "Of the screened four genes (ALCAM, CD22, CASP1, and CISH), CD22 is a sialic acid-binding immunoglobulin-like lectin (Siglec) that is highly expressed on B cell lymphomas and is a validated target for antibody and nanoparticle-based therapeutics on non-Hodgkin lymphoma." (PMID 34026619, 2021).
bacteremia (3 papers, 2014 to 2024). "While Eif2ak2 and Herc6 are implicated in bacterial sepsis, Rnf213 is associated with ubiquitylation of LPS, and Casp1 is a key factor in the inflammatory response in bacterial infection as detected in common upregulation." (PMID 38792580, 2024). "In contrast, high-grade bacteremia when sufficiently prolonged in mice expressing LR and PAFR led to more frequent and larger lesion formation, as evidenced in the Caspase-1 deficient mice." (PMID 25232870, 2014). "This may have been due to greater level of bacteremia experienced by the IL-1β deficient mice (WT n = 13, 2.47×108±4.36×107 CFU/mL blood; Caspase-1 KO n = 6, 7.82×108±3.18×108 CFU/mL blood; P = 0.012)." (PMID 25232870, 2014). "In addition, the mRNA expression of NLRP3, CASP1, and IL1B was altered in patients with SAB compared with healthy controls, indicating a modified priming state of the NLRP3 inflammasome during bacteremia." (PMID 31403210, 2019).
Barrett esophagus (3 papers, 2022 to 2025). Esophageal lesion lined with columnar metaplastic epithelium which is flat or villiform. "In esophageal adenocarcinoma research, inhibiting the enzyme caspase-1, which is crucial for pyroptosis, in organoid models significantly reduces the secretion of cytokines that drive disease progression." (PMID 40427552, 2025). "Studies have shown that caspase-1-mediated inflammation plays an important role in the pathogenesis of Barrett's esophagus and its progression to esophageal adenocarcinoma." (PMID 37302999, 2023). "Furthermore, organoid models of esophageal adenocarcinoma have been utilized to characterize the involvement of caspase-1 in disease progression, shedding light on the molecular mechanisms underlying pyroptosis in this cancer type." (PMID 40427552, 2025).
brain inflammation (3 papers, 2020 to 2023). "The use of caspase-1 activation biosensor mice to monitor inflammatory responses in vivo validates the presence of brain inflammation following repetitive mTBI." (PMID 37635235, 2023). "In vivo evidence provided by this study showed that caspase-1 inhibitor, VX765, significantly attenuated TBI-induced brain inflammation as well as neurological deficits." (PMID 32377306, 2020).
brucellosis (3 papers, 2014 to 2022). Brucellosis is a bacterial infection that spreads from animals to people via unpasteurized dairy products or by exposure to contaminated animal products or infected animals. "While the C-terminal region of mouse pyrin is uncharacterized, the human counterpart contains a SPRY domain that mediates interactions with Casp1 and pro-IL-1β and that is the site of mutations associated with Mediterranean fever." (PMID 24875775, 2014). "This study aims to investigate the expression levels of AIM2, NLRP3, ASC, and Caspase-1 inflammasomes in acute and chronic brucellosis patients to reveal the possible mechanism of Brucella immune escape." (PMID 36068262, 2022). "The AIM2 and NLRP3 inflammasomes are critical for caspase-1 activation and IL-1β secretion in macrophages and dendritic cells, which confer host protection during brucellosis." (PMID 35626718, 2022). "The expression levels of AIM2, NLRP3, ASC, and Caspase-1 were investigated in patients with acute brucellosis and chronic brucellosis as well as healthy controls." (PMID 36068262, 2022). "We speculate that Caspase-1 may play a major role in chronic brucellosis, which may relate to the overall gradual enhancement of the host immune response as the disease progresses." (PMID 36068262, 2022). "During the chronic phase of murine brucellosis, mice lacking the inflammasome component caspase-1 were more susceptible to brucellosis infection." (PMID 36068262, 2022). "Compared with healthy controls, patients with acute brucellosis show significantly higher AIM2 expression and significantly lower ACS expression, with no significant changes in NLRP3 but an increasing tendency of Caspase-1 genes." (PMID 36068262, 2022). "In patients with chronic brucellosis, AIM2 expression was significantly lower, while Caspase-1 expression was significantly higher than that of healthy volunteers." (PMID 36068262, 2022). "Compared with healthy controls, chronic brucellosis patients present an increasing tendency of NLRP3, significantly decreased AIM2 expression, and significantly increased Caspase-1 expression, with no significant changes in ASC." (PMID 36068262, 2022).
cerebral malaria (3 papers, 2013 to 2016). A sequestration of Plasmodium falciparum in the brain, which can cause coma and/or seizures. "Drugs targeting caspase-1 and IL-1β are already in clinical use and could be considered for the treatment of cerebral malaria." (PMID 27273825, 2016). "Studies in mice indicate that the inflammatory response to Plasmodium infection and the host susceptibility to experimental cerebral malaria are independent of Nlrp3 inflammasome-dependent caspase-1 activation of IL-1β and IL-18." (PMID 23405174, 2013). "While Dostert and colleagues demonstrated a partial protection to experimental cerebral malaria in NLRP3−/− mice, other studies reported that this pathological process occurs independent of NLRP3, ASC, Caspase-1, IL-1R, IL-1β, and IL-18." (PMID 24453977, 2014).
chronic cystitis (3 papers, 2015 to 2025). Recurrent infections of the urinary bladder. "KZMK significantly inhibited the expression of NLRP3, GSDMD, and Caspase-1 in LPS-induced cystitis, further confirming its anti-inflammatory effects." (PMID 40004227, 2025). "Inhibition of caspase 1/11 protected superinfected mice from chronic cystitis, suggesting a role for cytokines downstream of caspase activation including IL-1α and IL-1β, identified in our microarray of four-week bladders." (PMID 25569799, 2015). "We also saw a trend of caspase 1/11 inhibition in reducing the proportion of WT superinfected mice experiencing chronic cystitis to single infection levels." (PMID 25569799, 2015). "In our studies, we found that an increase in priming for chronic cystitis correlated with the bacterial ability to invade and replicate within the bladder tissue, and through hemolysin to activate caspase 1/11 leading to IL-1 secretion and bacterial replication." (PMID 25569799, 2015). "Activation of caspase 1/11 has been shown to contribute to epithelial cell death in vitro and exfoliation in vivo in C3H/HeN mice, suggesting that caspase-mediated exfoliation may expose the underlying epithelium upon which UPEC replicates during chronic cystitis (Nagamatsu et. al. in review)." (PMID 25569799, 2015).
cmo (3 papers, 2017 to 2024). "Previous studies have found that IL-1β secretion and mRNA expression levels of key inflammasome components, namely apoptosis-associated speck-like protein containing a CARD and Caspase-1, are abnormally increased in patients with chronic recurrent multifocal osteomyelitis." (PMID 38287380, 2024).
colorectal tumors (3 papers, 2015 to 2024). "It significantly decreased p-c-Jun, p-ERK and caspase-1 p20, three inflammatory markers, in colorectal tumors." (PMID 25881076, 2015). "Consistently, ablation of GSDMD in colorectal tumors did not result in any change in the activation of caspase 1, or IL-1 family cytokines or formation of NLRP3 or ASC specks." (PMID 38898209, 2024).